MPZ (myelin protein zero)
Description:
Is an adhesion molecule necessary for normal myelination in the peripheral nervous system. It mediates adhesion between adjacent myelin wraps and ultimately drives myelin compaction.
Synonyms: MPP; HMSNIB; CMT2I; CMT2J; P0; CMT1; CMT1B; CMT4E; CMTDI3; CMTDID; DSS
Tractability: Antibody: UniProt places it where antibodies can reach, with high confidence; its Gene Ontology location is reachable by antibodies, with high confidence; UniProt predicts a signal peptide or a membrane-spanning region.
Gene: Protein-coding gene on chromosome 1 (161,304,735 to 161,309,968, reverse strand). Ensembl gene ENSG00000158887.
Subcellular location: Cell membrane; Myelin membrane (Isoform L-MPZ)
Pathways (Reactome):
Developmental Biology: EGR2 and SOX10-mediated initiation of Schwann cell myelination
Gene Ontology:
Molecular function: protein binding; structural molecule activity
Biological process: cell aggregation; cell-cell adhesion; myelination; chemical synaptic transmission
Cellular component: plasma membrane; membrane; myelin sheath; synapse
Genetic constraint (gnomAD): Loss-of-function variants: 13 observed, 29.21 expected, observed/expected ratio (o/e) 0.45, 90% interval 0.29 to 0.71. The upper end of that interval is the gene's LOEUF score, 0.71, which puts it in group 2 of 6, group 1 being the genes least tolerant of losing a copy. Missense variants: 256 observed, 329.8 expected, observed/expected ratio (o/e) 0.78, 90% interval 0.7 to 0.86. Synonymous variants: 118 observed, 132.41 expected, observed/expected ratio (o/e) 0.89, 90% interval 0.77 to 1.04.
Gene-disease validity (ClinGen):
ClinGen rates the evidence that MPZ causes each of these diseases.
Charcot-Marie-Tooth disease (autosomal dominant): Definitive. An inherited degenerative disorder involving the peripheral nerves.
Homologues: Orthologues: chimpanzee MPZ (99% identical), macaque MPZ (99% identical), pig MPZ (96% identical), rabbit MPZ (96% identical), dog MPZ (96% identical), guinea pig MPZ (95% identical), mouse Mpz (94% identical), rat Mpz (94% identical), tropical clawed frog mpz (61% identical), zebrafish mpz (38% identical). Paralogues in human: MPZL1 (36% identical), MPZL3 (25% identical), MPZL2 (20% identical), SCN2B (19% identical), SCN4B (18% identical), JAML (17% identical).
Diseases named in the same sentence as MPZ in open-access papers:
MPZ is named in the same sentence as 59 diseases in open-access papers, as found by Europe PMC text mining. Sharing a sentence is not in itself a finding about the gene and the disease. The quoted sentences say what the papers report.
neuropathy (30 papers, 2010 to 2026). A disorder affecting the nervous system that manifests with pain, tingling, numbness, and/or muscle weakness. "Although the genetic mechanisms behind CMT1B are not fully understood, most mutations in the MPZ gene result in neuropathy by a gain-of-function mutation." (PMID 41595476, 2026). "Although the genetic mechanism of CMT1B is not fully understood, it is known that most mutations in the MPZ gene cause neuropathy through a toxic gain of function by the mutant protein." (PMID 39273178, 2024). "Variants in the MPZ gene have autosomal dominant inheritance, and if this variant was the cause of the neuropathy, the risk of affected offspring would be 50%." (PMID 37372933, 2023). "Supporting this explanation is the fact that we have recently demonstrated that patients who are haploinsufficient of MPZ have only a mild, late-onset neuropathy, much milder than the neuropathy caused by R98C or Ser63del MPZ mutations." (PMID 35501630, 2022). "One CMT1 patient with PMP22 duplication and MPZ variant (c.286A>C, p.K96Q) exhibited moderate neuropathy with infantile onset, while her father possessing MPZ variant was mildly affected with adolescence onset." (PMID 35153971, 2021). "The association of chronic cough and neuropathy has been reported in Holmes-Adie syndrome, MPZ (peripheral myelin protein zero) mutation associated neuropathy and autosomic dominant sensitive neuropathy with gastro-oesophageal reflux." (PMID 33011895, 2021). "Frameshift mutations in MPZ can cause intracellular accumulation of mutant proteins in the endoplasmic reticulum (ER) inducing apoptosis and subsequent neuropathy." (PMID 31336816, 2019). "The allelic heterogeneity in the MPZ gene is characterized by different types of neuropathy, in contrast to different disorders caused by mutations in the CACNA1A gene." (PMID 20385006, 2010). "It is noticeable that mutations that interfere with MPZ structure produce early-onset neuropathy, whereas those that affect MPZ-mediated transmission of signal and Schwann cell axonal interactions cause late-onset neuropathy." (PMID 41595476, 2026). "CMT1A and CMT1B are neuropathies caused by genetic abnormalities in peripheral myelin protein 22 and myelin protein zero, respectively, which are the main myelination-associated proteins in Schwann cells, and commonly show progressive SNHL starting in adolescence." (PMID 32453729, 2020). "A patchy neuropathy with conduction block and tonic pupils has been reported with MPZ mutations, as well, highlighting the genetic variability that might also mimic an inflammatory cause of neuropathy." (PMID 31336816, 2019). "Myelin protein zero is a key structural component of compact myelin, and over 100 mutations in this protein have been reported, which can give rise to neuropathies with either axonal, demyelinating, or intermediate features encompassing a wide range of severity." (PMID 22704856, 2012). "Advances in molecular genetics have identified key causative genes, including PMP22, MPZ, MFN2, TTR, EGR2, and CX32 (GJB1), which are implicated in Charcot–Marie–Tooth disease, Dejerine–Sottas syndrome, and related neuropathies." (PMID 41595476, 2026). "It is an inherited motor and sensor neuropathy due to mutation of the MPZ gene, which encodes the myelin protein zero that is involved in nerve myelination." (PMID 31412596, 2019). "De novo dominant variants predicted to affect function have been well reported in association with early-onset neuropathies in PMP22, MPZ and EGR2 [20, 21,]." (PMID 29511323, 2018). "MPZ mutations cause myelin deficiency and are responsible for Charcot-Marie-Tooth disease 1B (CMT1B) (OMIM 118200), CMT2I/J, and hypomyelinating or dysmyelinating neuropathy (Dejerine-Sottas disease)." (PMID 40964579, 2025).
neuropathy (continued). "There is increasing evidence that cytokines (such as TNF-α, IFN-γ), mutations in myelin protein zero (MPZ), Acanthamoeba and long-term hyperglycemia conditions induce Schwann cell death, then disrupt peripheral nerve support and neuropathy, and delay peripheral nerve regeneration." (PMID 38388913, 2024). "Hearing loss could develop simultaneously with neuropathy, in some patients with pathogenic variants in PRPS1 (n = 1), NEFL (n = 2), MPZ (n = 1), TRPV4 (n = 1); or at a distance in some cases of variants in SH3TC2 (n = 2) and ABHD12 (n = 1)." (PMID 31393079, 2019). "Regarding the genetical bases of the inherited neuropathies, the three most common forms have been identified as resulting from mutations in the Schwann cell‐related myelin genes for PMP22, Cx32 (GJB1), and P0 (MPZ)." (PMID 26250643, 2016). "Lastly, that circulating levels of MPZ mRNA were reduced in persons with T2D and DPN, discriminated DPN + from DPN- with high accuracy, and correlated with neuropathy scores as well as small- and large nerve fiber affection." (PMID 40192786, 2025). "These cases emphasise the heterogeneity of the phenotype of MPZ mutations, the fact that mutations in myelin proteins can result in disabling neuropathic pain and that there is no simple relationship between overall neuropathy severity and the degree of neuropathic pain." (PMID 22704856, 2012). "Certain patients carrying mutations in the myelin protein zero (MPZ) gene, the major component of PNS myelin, develop an axonal form of neuropathy in the absence of any detectable myelin defects." (PMID 32547370, 2020). "However, it still accounts for 7.5% of molecularly unassigned demyelinating CMT in the absence of PMP22 duplication, GJB1 mutations or MPZ mutations, as well as 1.9% of HNPP-like neuropathy of unknown genetic causes in Taiwan." (PMID 29127354, 2017).
Charcot-Marie-Tooth disease (10 papers, 2016 to 2025). "This deletion should render the Ig domain of MPZ misfolded and possibly subjected to ER-associated degradation, as is the fate of MPZ mutants associated with Charcot-Marie-Tooth disease." (PMID 37544648, 2023). "Mutations in the myelin proteins, such as PLP and MPZ, are associated with the neuropathic disorders in patients with Pelizaeus-Merzbacher disease and Charcot-Marie-Tooth disease, respectively." (PMID 32000863, 2020). "Mutations in the myelin protein zero gene are responsible for the autosomal dominant Charcot-Marie-Tooth disease (CMT)." (PMID 34925207, 2021). "The prominent worsening of PMD phenotype in mice lacking CHOP shows a sharp contrast in another disease model of peripheral demyelinating neuropathy, Charcot-Marie-Tooth disease (CMT), which is caused by mutations in the MPZ gene." (PMID 28286750, 2017).
Charcot-Marie-Tooth disease type 1B (4 papers, 2010 to 2025). A sensorineural peripheral polyneuropathy affecting approximately 1 in 2,500 individuals, and is the most common inherited disorder of the peripheral nervous system. "Many mutations in MPZ are associated with demyelinating neuropathies (Charcot-Marie-Tooth disease type 1B [CMT1B])." (PMID 36350884, 2022). "For example, previous studies found two synonymous mutations in TCOF1 and MPZ gene causing Charcot-Marie-Tooth disease type 1b and Treacher Collins syndrome." (PMID 28812016, 2017). "The importance of MPZ for proper myelination is underscored by the fact that MPZ protein-coding and splice-site mutations cause demyelinating Charcot-Marie-Tooth disease type 1B (CMT1B); however, mutations in transcriptional regulatory elements have not been reported to date." (PMID 21179557, 2010).
auditory neuropathy (3 papers, 2019 to 2022). A hearing disorder characterized by impaired transmission of signals through the auditory nerve, resulting in mild to severe hearing loss and poor speech perception. "There are several types, and more than 80 genes have been identified; particularly 2 of them, MPZ and PMP22, have been associated with auditory neuropathy." (PMID 36529647, 2022).
axonal neuropathy (3 papers, 2016 to 2025). Any nerve disorder affecting the axon of a nerve. "Variants in the myelin protein zero coding MPZ gene are responsible for a broad spectrum of peripheral demyelinating and axonal neuropathies, including different types of Charcot–Marie–Tooth diseases, challenging for genotype–phenotype correlation." (PMID 41363019, 2025). "Pathogenic variants in the MPZ gene have been associated with various subtypes of demyelinating and axonal peripheral neuropathies, including Charcot–Marie–Tooth (CMT) disease (types 1B, 2I, and 2J), juvenile Dejerine‐Sottas disease or Roussy‐Levy syndrome." (PMID 41363019, 2025). "In this report, we described a large Chinese family with late-onset axonal neuropathy, pupil abnormalities, and hearing loss associated with a novel mutation in MPZ." (PMID 27774063, 2016).
Charcot-Marie-Tooth disease type 1 (3 papers, 2013 to 2022). Charcot-Marie-Tooth disease type 1 (CMT1) is a group of autosomal dominant demyelinating peripheral neuropathies characterized by distal weakness and atrophy, sensory loss, foot deformities, and slow nerve conduction velocity. "Mutations in MPZ were associated with the peripheral neuropathy Charcot-Marie-Tooth disease type 1." (PMID 35754711, 2022). "Charcot–Marie-Tooth type 1 are inherited demyelinating diseases affecting peripheral nerves which are caused in most patients by mutations in Pmp22 (CMT1A), MPZ (CMT1B), and GJB1 genes (CMT1X; see for review Suter and Scherer, 2003)." (PMID 24194699, 2013). "Charcot-Marie-Tooth disease type 1A (CMT1A), caused by duplication of the peripheral myelin protein 22 (PMP22) gene, and CMT1B, caused by mutations in myelin protein zero (MPZ) gene, are the two most common forms of demyelinating CMT (CMT1), and no treatments are available for either." (PMID 35501630, 2022).
congenital hypo-myelinating neuropathy (3 papers, 2010 to 2021). "MPZ mutations are closely associated with diseases such as Charcot–Marie–Tooth neuropathy type 1B, Dejerine–Sottas syndrome, and congenital hypo-myelinating neuropathy." (PMID 34071138, 2021). "Clinically missense mutations in the MPZ gene can cause congenital hypomyelinating neuropathy (CH), DSS, CMT type 1, CMT type 2 and intermediate CMT." (PMID 20385006, 2010). "Mutations in MPZ have been associated with different Charcot–Marie–Tooth disease (CMT) phenotypes (CMT1B, CMT2I/J, CMTDI), Dejerine–Sottas syndrome, and congenital hypomyelination neuropathy." (PMID 27774063, 2016).
demyelinating peripheral neuropathy (3 papers, 2010 to 2016). "The frequency of PMP22 duplications among the demyelinating polyneuropathy patients in this material was lower than average (18.7%), whereas the frequency of MPZ mutations (6.0%) and GJB1 mutations (6.7%) were close to average." (PMID 24053775, 2013). "Finally, mutations in SOX10 target genes including those encoding peripheral myelin protein 22 (PMP22), myelin protein zero (MPZ), and gap junction beta 1 (GJB1) cause demyelinating peripheral neuropathy." (PMID 27821050, 2016). "Mutations in MPZ, SOX10, and EGR2 have been implicated in demyelinating peripheral neuropathies, suggesting that components of this transcriptional network are candidates for harboring disease-causing mutations (or otherwise functional variants) that affect MPZ expression." (PMID 21179557, 2010). "The identification of null MPZ alleles in patients with CMT1B suggests that there is a threshold in the amount of MPZ required for proper myelination; in support of this notion, mice that are heterozygous for an Mpz-knockout allele develop a late-onset peripheral demyelinating neuropathy." (PMID 21179557, 2010).
Déjérine-Sottas syndrome (3 papers, 2003 to 2023). "For example, the Tyr82Cys variant in MPZ was described in patients with both CMT1 and Dejerine-Sottas Syndrome (DSS) and the Tyr82His change was identified in a milder late-onset phenotype CMT2 patient." (PMID 36738336, 2023). "However, several mutations of dominant inheritance in the peripheral myelin protein 22 gene and the peripheral myelin protein zero gene have been reported in patients with Dejerine-Sottas disease." (PMID 14666293, 2003).
demyelinating disease (2 papers, 2021 to 2024). A broad group of disorders that affect the myelin sheaths that cover the neurons. "One of the other representative PNS demyelinating diseases is Charcot-Marie-Tooth disease which is induced by the gene mutation including myelin protein zero (P0) and PMP223–6." (PMID 34413421, 2021).
Hearing impairment (2 papers, 2014 to 2025). A decreased magnitude of the sensory perception of sound. "Although hearing loss was only mild in the index patient, it was attributed to the underlying MPZ variant, as other MPZ mutations have previously been described that manifest as hearing loss and hearing impairment." (PMID 40964579, 2025). "However, the proximity of the 1q23.3 breakpoint to two hearing impairment (HI) loci, DFNA49 and DFNA7, and in the vicinity of the myelin protein zero (MPZ) gene, prompts speculation on this break’s correlation with the hearing loss observed in congenitally infected infants." (PMID 24576846, 2014).
hereditary motor and sensory neuropathy (2 papers, 2020 to 2025). A group of slowly progressive inherited disorders affecting motor and sensory peripheral nerves. "The MPZ gene is one of the genes responsible for Charcot–Marie–Tooth (CMT) disease, which is also known as hereditary motor and sensory neuropathy (HMSN)." (PMID 32170207, 2020).
melanoma (2 papers, 2024 to 2025). A malignant, usually aggressive tumor composed of atypical, neoplastic melanocytes. "A positive correlation between the expressions of COL1A1 and MPZ with EGR3 expression in melanoma patients was also observed." (PMID 38973154, 2024). "The up‐regulation of COL1A1 and MPZ caused by EGR3 overexpression was validated in both A375 and B16‐F10 melanoma cell lines." (PMID 38973154, 2024). "Conversely, communication patterns of target cells indicated that incoming melanoma cell signaling was predominantly characterized by pattern 1, which including pathways such as CD99 and TNF as well as PARS, TGFb, AGRN, and MPZ." (PMID 39781353, 2025).
multiple sclerosis (2 papers, 2016 to 2024). A progressive autoimmune disorder affecting the central nervous system resulting in demyelination. "Patients with MPZ mutations exhibit a wide range of phenotypic variability beyond the peripheral nervous system, including pupillary abnormalities, hearing loss, diaphragmatic weakness or chronic cough, restless-leg-like symptoms and multiple sclerosis." (PMID 27774063, 2016).
neurofibroma (2 papers, 2019 to 2023). An intraneural or extraneural neoplasm arising from nerve tissues and neural sheaths. "Neurofibroma tumor nuclei remain most similar to Schwann cells, with expression of markers such as S100B, PMP2, MPZ and ERBB3." (PMID 37164978, 2023). "We found decreased gene expression on the SC differentiation/myelination markers (PMP22, MPZ, and MBP) in both mouse and human plexiform neurofibromas versus WT nerve controls." (PMID 31032403, 2019).
Anisocoria (1 paper, 2016). Anisocoria, or unequal pupil size, may represent a benign physiologic variant or a manifestation of disease. "Furthermore, anisocoria [PMP22, MPZ, MFN2, SH3TC2; FYVE, RhoGEF, and PH domain‐containing protein 4 (FGD4) gene], miosis (PMP22, MPZ) and mydriasis (MPZ) have been described previously." (PMID 27088055, 2016).
autonomic dysfunction (1 paper, 2024). "It is not yet known how MPZ mutations cause autonomic dysfunction, and the role of MPZ in the autonomic nervous system needs to be investigated in detail in future studies." (PMID 38396973, 2024).
Cognitive impairment (1 paper, 2023). Abnormal cognition is characterized by deficits in thinking, reasoning, or remembering. "In addition, we observed some downregulated genes (such as MPZ, GJB1, CDH15, KCNQ3, and PLP1) in K-NSC cells, and abnormal expression of these genes has been reported to cause cognitive impairment, epilepsy, spasticity, and myelin abnormalities, which are similar to the disease symptoms of GLD." (PMID 37076788, 2023).
diabetic neuropathy (1 paper, 2021). A chronic, pathological complication associated with diabetes mellitus, where nerve damages are incurred due to diabetic microvascular injury involving small blood vessels that supply these nerves, resulting in peripheral and/or autonomic nerve dysfunction. "Circulating mRNA of myelin protein zero was decreased significantly in participants with diabetic neuropathy (p < 0.001), whereas neurofilament light chain protein showed increased levels in participants with diabetic neuropathy (p < 0.05)." (PMID 34480211, 2021).
Hypertension (1 paper, 2022). The presence of chronic increased pressure in the systemic arterial system. "Differentially expressed PNMT, MPZ, RAB3C, and CD36 can be potential targets for AMH, providing a theoretical basis for mechanistic exploration of AMH along with hypertension." (PMID 36583008, 2022). "Of note, PNMT, MPZ, RAB3C, and CD36 are found to differentially expressed and can be potential targets for AMH, providing a theoretical basis for mechanistic exploration of AMH along with hypertension." (PMID 36583008, 2022).
Mitochondrial myopathy (1 paper, 2025). "In a recent study, muscle biopsy in patients with MPZ-gene mutations and either CMT1 or CMT2 phenotypes showed alterations indicative of mitochondrial myopathy, of unexplained mechanism." (PMID 40009145, 2025).